PTP4A1 (protein tyrosine phosphatase 4A1)
Diseases named in the same sentence as PTP4A1 in open-access papers (continued):
Sharing a sentence is not in itself a finding about the gene and the disease.
infection (1 paper, 2009). The state of being infected such as from the introduction of a foreign agent such as serum, vaccine, antigenic substance or organism. "Neither of these genes appeared to respond to infection or to be differentially expressed, although Ptp4a1 was highly expressed throughout the infection (not shown)." (PMID 19365556, 2009).
metabolic disorders (1 paper, 2023). "Based on the opposite phenotype and co-localization in the subcellular compartment between PTP1B and PTP4A1, the beneficial potential of PTP4A1 in metabolic disorders such as NAFLD might be considerable." (PMID 36793871, 2023). "Our current study provides a novel function of PTP4A1 in metabolic disorders; hence, modulating PTP4A1 may be a potential therapeutic strategy against hepatosteatosis-related diseases." (PMID 36793871, 2023).
PTP4A1 also shares sentences with these, for which no sentence is quoted: colorectal cancer (4 papers); liver cancer (2); alcoholism (1); autoimmune disease (1); chronic obstructive pulmonary disease (1); ciliopathy (1); glioblastoma (1); Liver cirrhosis (1); Moyamoya disease (1); nasopharyngeal carcinoma (1); pancreatic cancer (1); prostate carcinoma (1); salivary gland tumor (1); Stroke (1); tongue squamous cell carcinoma (1).